MUC1 (mucin 1, cell surface associated)
Diseases named in the same sentence as MUC1 in open-access papers (continued):
Sharing a sentence is not in itself a finding about the gene and the disease.
colorectal cancer (continued). "The expression levels of MUC1 and MUC5AC correlate significantly with the tumor grade of colorectal cancer and are therefore used as markers for assessing the prognosis of GC patients." (PMID 34207342, 2021). "A MUC1-poly-ICLC vaccine has been tested for patients with advanced adenomatous polyps, which are a precursor to colorectal cancer." (PMID 33869008, 2021). "Mucin 1 (MUC1) is overexpressed in different cancer cells (breast, prostate, non-small cell lung cancer (NSCLC) and colorectal cancer) that are the target for tacetomide." (PMID 29385755, 2018). "TCM targets mucin 1 (MUC1), which is overexpressed in different cancer cells, including breast, prostate, non-small cell lung cancer (NSCLC) and colorectal cancer." (PMID 28346375, 2017). "The current study comprises the largest analysis of MUC1 and MUC3 expression in colorectal cancer to date; including 463 consecutively treated representative patients, who were representative of the colorectal cancer population within the UK." (PMID 17349047, 2007). "Using high throughput tissue microarray technology we assessed the prognostic value of MUC1 and MUC3 expression in the largest cohort of colorectal cancer patients to date." (PMID 17349047, 2007). "In other words, the impact of C1GALT1 on MUC1 glycosylation has a certain influence on the development of colorectal cancer, although the specific mechanism is not yet fully understood." (PMID 38699634, 2024). "The experiments showed that MUC1 was not expressed in the colorectal cancer cell lines Caco-2 and HCT116, while it was highly expressed in the colorectal cancer cell lines HT29 and SW620." (PMID 35784721, 2022). "Additionally, researches have shown that LINC01296 can regulate MUC1 through the PI3K/AKT pathway and is involved in colorectal cancer progression." (PMID 34515611, 2021). "The MUC1 oncoprotein is predictive for tumor progression in colorectal cancers, including those related to HNPCC (Hereditary nonpolyposis colorectal cancer)." (PMID 28153010, 2017). "This vaccination setting was recently reported for a Muc-1 peptide-based vaccine in subjects with advanced colonic adenomas (but not yet colorectal cancer)." (PMID 24379816, 2013). "Since the percentage of colorectal cancers expressing MUC1 is very high, MUC1 testing results are not required prior to inclusion." (PMID 22494623, 2012). "Recently, seromic profiling of colorectal cancer patients with a glycopeptide microarray identified abs to aberrant glycopeptides derived from MUC1 and MUC4 that may be of use for colorectal cancer screening." (PMID 24212946, 2011). "This study investigates the role of MUC1 and MUC3 as prognostic markers in colorectal cancer." (PMID 17349047, 2007). "However, there are no available small molecules or peptides that target MUC1 for treating MUC1-positive colorectal cancers." (PMID 28153010, 2017). "However, there has been no direct proof that MUC1 is essential for colorectal cancer cell growth and survival." (PMID 28153010, 2017). "IHC data confirmed that EGFR and MUC1 were highly expressed on LUAD and colorectal cancer (CRC) clinical samples but not on various normal tissues." (PMID 39664199, 2024). "Patients with breast and colorectal cancer express anti-MUC1 IgG antibodies at much higher frequencies than healthy individuals and both MHC-restricted and non-restricted T-cell responses against MUC1 have also been detected in cancer patients." (PMID 23166757, 2012).
COVID-19 (74 papers, 2020 to 2025). A disease caused by infection with severe acute respiratory syndrome coronavirus 2. "MUC1 mRNA expression was, in addition to its association with COVID-19 presentation, identified as a major discriminant for critically ill COVID-19 patients, which is in line with what has previously been reported." (PMID 34448730, 2021). "Last, we show that ATP11A, DPP9, NPNT, and MUC1 are highly expressed in lung alveolar epithelial cells, both in COVID-19 uninfected and infected samples." (PMID 37794074, 2023). "All above associations of alternative splicing, except for MUC1 and PMF1, were more pronounced as the severity of the COVID-19 outcome increased." (PMID 37794074, 2023). "Compound R406, the active metabolite of FDA-approved Fostamatinib that inhibits MUC1 expression is now in clinical trials for hospitalized patients with advanced COVID-19." (PMID 37561789, 2023). "The severe symptoms of COVID-19 express as virus-induced pneumonitis, followed by a sustained release of cytokines and macrophage-derived IL-6, which upregulates MUC1 in human colon cancer cell lines." (PMID 35315705, 2022). "The pathway depicting the altered glycosylation of MUC1 as a promoter of chronic inflammatory conditions (WP4480) is more active with all proteins more abundant in COVID-19." (PMID 36189295, 2022). "The serum concentrations of KL-6/MUC1 in the terminally ill COVID-19 patients validated KL-6/MUC1 as a prognostic biomarker of the severity of COVID-19 disease." (PMID 35315705, 2022). "The increased expression of MUC1 in the patients who succumbed to the COVID-19 infection further necessitates the expansion of clinical trials that involve the use of MUC1 inhibitors to treat patients with COVID-19." (PMID 35315705, 2022). "MUC1 mRNA expression was significantly higher in the blood of critically ill patients with COVID and those with mild COVID-19 compared with healthy controls." (PMID 34448730, 2021). "Given that MUC1 can serve as an antiinflammatory factor in the airways later in the disease course, its role in severe COVID-19 remains to be further investigated." (PMID 34448730, 2021). "A recent study compared levels of MUC5AC, MUC1 and MUC1-CT between critical ill COVID-19 patients and healthy controls, finding a significantly higher level of those proteins in the patients’ mucus." (PMID 34828448, 2021). "A significant difference in MUC1 mRNA expression was also seen between the critically ill COVID-19 patients and the mild non–COVID-19 patient group." (PMID 34448730, 2021). "In conclusion, we have used genetic determinants of alternative splicing and COVID-19 outcomes obtained from large-scale studies and found compelling evidence that splicing events in OAS1, ATP11A, DPP9, NPNT, MUC1, and PMF1 have causal effects on COVID-19 severity and susceptibility." (PMID 37794074, 2023). "MUC1 and PMF1 splicing is associated with COVID-19 susceptibility." (PMID 37794074, 2023). "Since elevated circulating levels of KL-6 indicate disruption of the alveolar epithelial lining, we hypothesized that it could be advantageous analysing KL-6/MUC1 in a group of severe COVID-19-positive patients, to better risk stratify and triage them." (PMID 37386665, 2022). "By using the same approach, we also showed that age and mRNA expression of MUC1, MUC2, MUC4, MUC6, MUC13, MUC16, and MUC20 were the most accurate variables associated with the presence of COVID-19 among symptomatic patients (AUCROC = 91.8%; sensitivity: 90.6%; specificity: 93.3%)." (PMID 34448730, 2021). "In addition, a dominant MUC1 staining was also shown in lung tissue from deceased COVID-19 patients and in pulmonary biopsies collected from patients with an exudative phase of COVID-19, further underlining a potential role for MUC1 in the severe course of the disease." (PMID 34448730, 2021).
COVID-19 (continued). "Similar with findings from CPASSOC, we found shared genes between COVID-19 and cancers that are related to hematologic systems (ABO), immune function (MUC1, PLEKHM1), and cell proliferation (KANSL1-AS1)." (PMID 37636041, 2023). "In 23 lung COVID-19 autopsy donor tissue samples from GSE17166820, the expression of ATP11A, DPP9, MUC1, and NPNT were also enriched in alveolar type 1 and 2 epithelial cells." (PMID 37794074, 2023). "In the course of COVID-19, elevated levels of gel-forming MUC5AC and shed MUC1 can be detected in sputum aspirated from the trachea of patients and high production of MUC5AC was observed in SARS-CoV-2 infected primary respiratory cultures." (PMID 37561789, 2023). "In contrast, a recent study has described elevated MUC1 and MUC5AC protein levels in airway mucus of critically ill COVID-19 patients." (PMID 35131898, 2022). "MUC1, MUC2, MUC4, MUC16, and MUC20 mRNA expression strongly correlated with COVID-19 severity, of which MUC1 and MUC20 mRNA expression also associated significantly with age and MUC16 and MUC20 mRNA expression with sex." (PMID 34448730, 2021). "A strong positive correlation was also seen between MUC1 and MUC2 mRNA expression and between MUC16 and MUC20 mRNA expression and specifically in the mild COVID-19 patient group." (PMID 34448730, 2021). "There are two positive KEGG pathways related to MUC1 (Coronavirus disease, COVID-19 and Ribosome) and two negative KEGG pathways related to MUC1 (Staphylococcus aureus infection and Intestinal immune network for IgA production)." (PMID 35879749, 2022). "The upregulation of KL-6/MUC1 during acute lung injury and ARDS led to the hypothesis that there may be beneficial effects of fostamatinib in patients suffering from COVID-19 lung injury." (PMID 35315705, 2022). "Taken together, these expression evidence suggests that the transcriptional splicing—COVID-19 outcome relationships for ATP11A, DPP9, MUC1, and NPNT were likely to be relevant in lung tissue and these signals may be especially important in alveolar epithelial cells." (PMID 37794074, 2023).
melanoma (69 papers, 1998 to 2025). A malignant, usually aggressive tumor composed of atypical, neoplastic melanocytes. "Other CAMs, such as MUC1 (MUC1), a cell–cell adhesion molecule implicated in lung metastasis in melanoma, have also been shown to resist anoikis in other epithelial cancers." (PMID 34439879, 2021). "Aberrant MUC1, which is substantially expressed in melanoma cells, has been implicated in the induction of immunosuppressive tumor microenvironment." (PMID 33692796, 2021). "The aberrant MUC1 is present in melanoma and has been implicated in its metastasis." (PMID 33692796, 2021). "Immunization with the MUC1 vaccine in the murine B16/MUC1+ melanoma model induced greater MUC1-specific CD8+ T cell response compared to HSP70 or deletion of the C-terminal domain alone." (PMID 41012179, 2025). "in a melanoma mouse model found that overexpression of TRAF6 significantly enhanced MUC1-specific Th1 and Tc1 responses while reducing the proportion of Tregs, thereby ameliorating the immunosuppressive state and inhibiting tumor growth." (PMID 38361923, 2024). "In melanoma-related research, MUC1 and MUC16 have demonstrated distinct roles in tumor progression and immune responses." (PMID 38361923, 2024). "In melanoma treatment, immunotolerance induced by MUC1 vaccination was reversed by anti-PD-L1 antibodies, a process involving an increased CD80/PD-L1 ratio, promotion of dendritic cell maturation, activation of Th1 and Tc1 cells, and inhibition of Treg cells." (PMID 38361923, 2024). "A recent study has shown that MUC1 participates in tumor cell migration as a driving force in metastasis in lung cancer, as well as melanoma." (PMID 38067178, 2023). "As a potential therapeutic adjuvant, PPAS was formulated with MUC1 peptides as a vaccine against B16/MUC1 melanoma." (PMID 35890342, 2022). "Cytosine-guanosine nucleotide (CpG) enhanced the antitumor effect of BCG HSP65 when anchored to tumor antigens Her2 or tumor-associated antigen Mucin 1 (MUC1), both expressed in melanoma cells." (PMID 32635668, 2020). "Pre-treatment of MUC1-expressing human melanoma ACA19+ cells with galectin-3 before application of the cells to HUVEC monolayers resulted in a ∼50% increase of cell adhesion in comparison to the BSA-treated control cells." (PMID 26160844, 2015). "B6 mice inoculated with B16-F10-MUC1 cells and MUC1-specific T cells completely rejected the melanoma cells, and all of the mice survived." (PMID 23028615, 2012). "The MUC1-specific T cells were mixed with B16-F10 melanoma cells transfected with MUC1 cDNA (B16-F10-MUC1) and subcutaneously injected into naïve B6 or MUC1.Tg mice." (PMID 23028615, 2012). "MUC1.Tg mice have previously been shown to be immunologically tolerant to MUC1 when the immune response to B16 melanoma cells transfected with MUC1 cDNA was investigated." (PMID 23028615, 2012). "In some approaches, less relevant antigens were used such as melanoma cell lines stably transfected to express viral antigens of hepatitis B virus or HPV (human papillomavirus) or human oncogenes like Mucin 1 (MUC-1)." (PMID 21197271, 2010). "Our previous study demonstrated that B27.29 anti-MUC1 mAb, directed against the PDTRPAP epitope within the VNTR region of MUC1, induces MUC1 cell surface polarization and increases human melanoma cell adhesion to endothelium." (PMID 20565834, 2010). "MUC1 could interact with ErbB2 and other RTKs involved in the PI3K/AKT signaling pathway, which in turn is associated with melanoma progression and acquired BRAF inhibitor resistance." (PMID 38067178, 2023). "Moreover, the antibodies produced strongly bound to MUC1-expressing melanoma B16-MUC1 cells, demonstrating the potential of MUC1-Qβ as an anti-cancer vaccine." (PMID 36714624, 2022).
melanoma (continued). "In a previous study, we found that the combination of the Toll-like receptors 9 (TLR9) agonist CpG oligodeoxynucleotides 1826 (CpG 1826) and M-M inhibited the growth of melanoma B16-MUC1 cells subcutaneously transplanted into mice and mediated MUC1-specific humoral and cellular immune responses." (PMID 36142800, 2022). "The transmembrane glycoprotein mucin 1 (MUC1) is a novel tumoral antigen on melanoma cells." (PMID 33692796, 2021). "Moreover, only mice immunised with AntpMAPMUC1tet + CpG showed delayed tumour growth when challenged with the melanoma B16 MUC1 expressing tumour cell line." (PMID 30200528, 2018). "A remarkable synergistic effect of adjuvant immune stimulation by a combination of several approaches combining cholera toxin (subunit B), aluminum hydroxide gel, and CpG oligo deoxynucleotide on induction of Muc1-directed T cells was shown in a B16 melanoma mouse model." (PMID 30112704, 2018). "Similar results were also observed with MUC1-transfected human melanoma cells." (PMID 25275599, 2014). "In addition, combining a MUC1 vaccine with mANT2shRNA-1 (short-hairpin RNA) therapy, compared with a single therapy, induced highly potent anti-MUC1 immunity and anticancer activity to resist benign MUC1-positive mammary fibroadenomatosis cell (murine melanoma cell) tumors." (PMID 35883508, 2022). "Moreover, targeting MUC1 has substantially reduced the metastasis of melanoma." (PMID 33692796, 2021). "In this study, we show for the first time that B16 melanoma cells depend on both CIN85 and MUC1 to metastasize to the lung." (PMID 24072600, 2013). "No cytolytic activity was detected when non-melanoma-reactive, HLA-A2+, MUC-1 CTLs were co-incubated with melanoma-entrained CD8+T-APCs." (PMID 25671577, 2015). "In contrast, MUC1-negative melanoma cell-lines, SK-mel-28 and SK-mel-1, and the MUC1-negative ovarian cell-line, ES-2, consistently failed to react (low geometric mean) with all tested antibodies, demonstrating antibody selectivity to MUC1 SP." (PMID 24416403, 2014). "When tested in vivo in a tumor metastasis model of B16 melanoma, mice injected with CIN85-depleted melanoma cells exhibited few or no lung metastasis and, similarly to the in vitro results, overexpression of MUC1 recovered the shCIN85-reduced metastatic process." (PMID 24072600, 2013). "On the other hand, passive transfer of MUC1-specific antibodies did not affect the growth of MUC1 expressing, experimentally transplanted melanomas in a mouse model." (PMID 12966437, 2003). "MF59 alone with HSP65-MUC1 could not inhibit the growth of MUC1+ B16 melanoma cells whereas MF59-YW002 did inhibit growth." (PMID 27472370, 2016). "To exclude the possibility that non-specific adherence of melanoma fragments, rather than CD8+T-APCs, account for CTL activation, we co-cultured MUC-1-reactive CD8+ T cells with 624mel." (PMID 25671577, 2015). "Lysis induced by all anti-MUC1 antibodies was highly significant (p<0.001 in Student's t-test) in MUC1-expressing tumor cell lines, when compared to the ovarian cell line ES-2, the melanoma cell line SK-mel-1 and NHEC, three MUC1-negative cell lines." (PMID 24416403, 2014). "We confirmed this finding in the human melanoma cell line DM6, mouse melanoma cells B16 and mouse lymphoma RMA, that were stably transfected with either MUC1/22TR or MUC1/Y, an isoform of MUC1 lacking most of the extracellular domain." (PMID 24072600, 2013).